PRIM1 (DNA primase subunit 1)
Diseases named in the same sentence as PRIM1 in open-access papers:
PRIM1 is named in the same sentence as 41 diseases in open-access papers, as found by Europe PMC text mining. Sharing a sentence is not in itself a finding about the gene and the disease. The quoted sentences say what the papers report.
breast cancer (8 papers, 2017 to 2023). A primary or metastatic malignant neoplasm involving the breast. "Previous studies have implied that PRIM1 closely related to osteosarcoma, pancreatic cancer, and breast cancer is profoundly implicated in cancer progression." (PMID 32908930, 2020). "Two of these genes, CTNNA3 and PRIM1, have been previously associated with breast cancer." (PMID 37345113, 2023). "This identified thirty-one unique genes, of which five have previously been associated with breast cancer (LGR6, NR3C2, LOC105377563, CTNNA3, PRIM1)." (PMID 37345113, 2023). "High PRIM1 expression was connected with poorly differentiated tumors and poorer survival outcomes in breast cancer." (PMID 32908930, 2020). "PRIM1 plays an important role in the strict control of the DNA replication fork during tumor cell proliferation and was shown to be involved in estrogen-induced breast cancer formation through activation of the G2/M cell cycle checkpoint." (PMID 34820188, 2021). "Although emerging studies have indicated the potential roles of PRIM1 in the malignant behaviors of breast cancer, the expression features and functions of PRIM1 in HCC remain unclear." (PMID 33622397, 2021). "However, in breast cancer and lung cancer it was found that the expression level of PRIM1 in tumor tissue was higher." (PMID 33869278, 2021).
hepatocellular carcinoma (4 papers, 2020 to 2021). A malignant tumor that arises from hepatocytes. "Our study demonstrated that PRIM1 contributed to the proliferation of hepatocellular carcinoma cells in vitro and in vivo." (PMID 33046981, 2020). ">As revealed by an analysis of the Integrative Molecular Database of Hepatocellular Carcinoma (HCCDB) and ONCOMINE databases, the PRIM1 expression was remarkably enhanced in HCC tissues." (PMID 32908930, 2020). "In this study, we initially discovered that PRIM1 expression was significantly increased in HCC using TCGA and GEO databases, which is entirely consistent with the data from the Integrative Molecular Database of Hepatocellular Carcinoma (HCCDB) and ONCOMINE databases." (PMID 32908930, 2020).
osteosarcoma (4 papers, 2004 to 2020). A usually aggressive malignant bone-forming mesenchymal neoplasm, predominantly affecting adolescents and young adults. "Pervious studies have shown the amplification GLI, CHOP, SAS, HMGI-C, CDK4, HDM2, and PRIM1 from 12q13-q15 region in osteosarcoma." (PMID 15298715, 2004).
liver cancer (3 papers, 2020 to 2021). An epithelial or non-epithelial malignant neoplasm that arises from the liver. "In the future study, we will screen the downstream target gene of PRIM1 by gene microarray technique to further explain the signaling transduction of PRIM1 during the development of liver cancer." (PMID 33046981, 2020). "Bioinformatics method was used to obtain the information about PRIM1 gene, and the correlation between PRIM1 and clinical pathological stage of liver cancer was analyzed by Mann-Whitney U test." (PMID 33046981, 2020). "We selected RNAseq data of 50 paired liver cancer samples from the Cancer Gene Atlas (TCGA), and then bioinformatics methods and Mann-Whitney U test were used to analyze the correlation between PRIM1 and the clinical pathological stage of liver cancer." (PMID 33046981, 2020). "In our study, we analyzed the differentially expressed gene PRIM1 related to liver cancer from 50 paired tumor tissues with complete information from TCGA, QPCR results showed that PRIM1 was expressed in BEL-7404, BEL-7402, HepG2 and SMMC-7721 cells." (PMID 33046981, 2020). "PRIM1 card gene was screened by TNM standardization control, CBV quality control and log2 statistics, Mann-Whitney U test was used to analyze the significant expression difference of PRIM1 on different pathological stages of liver cancer (P<0.05)." (PMID 33046981, 2020). "Like PRIM1, GMPS was found to be expressed higher in tumor tissues and peripheral blood of liver cancer patients." (PMID 33869278, 2021). "So, interference of PRIM1 expression can inhibit the proliferation of BEL-7404 and SMMC-7721 cells, as well as induce the apoptosis of liver cancer cells." (PMID 33046981, 2020). "Moreover, liver cancer patients with an increased expression level of KIF14 (p = 0.006), PRIM1 (p = 0.013), and RFC4 (p < 0.001) also had poorer outcomes." (PMID 34681056, 2021). "PRIM1 plays an important role during oncogenesis, however it has never been reported in liver cancer, and thus our objective is to explore the role of PRIM1 in liver cancer." (PMID 33046981, 2020).
microcephaly (3 papers, 2020 to 2024). A congenital or acquired developmental disorder in which the circumference of the head is smaller than normal for the person's age and sex. "The PRIM1 deficiency is known to cause lymphopenia along with severe growth retardation, microcephaly and “triangular face”." (PMID 36574455, 2022). "In summary, we identify a novel hypomorphic PRIM1 variant c.103 + 2 T > G associated with the most attenuated phenotype of PRIM1 deficiency described so far with no microcephaly or developmental delay and in overall good health under IRT." (PMID 38773012, 2024). "Most individuals with MPD caused by POLA1 variants have growth retardation and microcephaly without such features, and facially PRIM1 deficiency appears distinct from these and individuals with POLE-associated IMAGe syndrome." (PMID 33060134, 2020).
lung adenocarcinoma (2 papers, 2016 to 2025). A carcinoma that arises from the lung and is characterized by the presence of malignant glandular epithelial cells. "Our findings suggest thatDEGs encoding subunits of NADH, PRIM1, MCM3, MAPK1, STAT3, RAF1, and JAK1 might beassociated with the development of lung adenocarcinoma." (PMID 26840709, 2016).
microcephalic primordial dwarfism (2 papers, 2021). Primordial dwarfism with microcephaly. "PRIM1 is usually associated with Seckel syndrome and telangiectatic osteosarcoma disease." (PMID 34394704, 2021).
Airway obstruction (1 paper, 2022). Obstruction of conducting airways of the lung. "The impact of PRIM1 on craniofacial morphology may contribute to OSA by causing a narrow airway, and thereby increasing the risk of airway obstruction during sleep; however, an inflammatory mechanism is also possible." (PMID 36574455, 2022).
anaemia (1 paper, 2024). "In line with this, biallelic PRIM1 variants that affect DNA replication fork stability are reported in patients with primordial dwarfism with episodic thrombocytopenia and anaemia." (PMID 39198715, 2024).
B cell deficiency (1 paper, 2024). A broad classification of disorders where circulating numbers of B lymphocytes are decreased or ineffective. "Here we add 3 novel patients to show that B-cell deficiency in PRIM1 deficiency is markedly variable and that the severity of the syndromic manifestations is not indicative of the immunological phenotype and its clinical consequences." (PMID 38773012, 2024). "In summary, the B-cell deficiency in PRIM1-deficiency is markedly variable and the severity of syndromic manifestations is not predictive of the immunological phenotype." (PMID 38773012, 2024).
breast tumors (1 paper, 2023). "PRIM1, which encodes DNA primase polypeptide 1, has been found to be overexpressed in breast tumors." (PMID 37345113, 2023).
Cirrhosis (1 paper, 2007). A chronic disorder of the liver in which liver tissue becomes scarred and is partially replaced by regenerative nodules and fibrotic tissue resulting in loss of liver function. "PRIM1 was found by microarray analysis to be down-regulated during cirrhosis, dysplasia and very early HCC, followed by increasing up-regulation in the successive stages of HCC." (PMID 17640361, 2007).
disc degeneration (1 paper, 2025). "In severe disc degeneration, RCOR2, STAT3, NOTCH1, SP1, and SART1 expression were elevated, while PRIM1 and LYAR expression levels were significantly reduced." (PMID 40799650, 2025).
esophageal cancer (1 paper, 2025). A primary or metastatic malignant neoplasm involving the esophagus. "Furthermore, miRNA-based biomarkers (e.g., miR-132-3p, miR-576-5p) correlate with radiosensitivity in esophageal cancer; glioblastoma genes like POLQ, PRIM1, and RPA1 are linked to radioresistance, while miR-153-3p overexpression enhances radiosensitivity." (PMID 40277781, 2025).
gastric carcinoma (1 paper, 2025). A carcinoma that arises from epithelial cells of the stomach. "It was reported that the expression of PRIM1 was upregulated in gastric carcinoma, and it was correlated with poor prognosis." (PMID 40216745, 2025).
hypogammaglobulinemia (1 paper, 2024). "Biallelic mutations in PRIM1 are associated with a primordial dwarfism syndrome with variable hypogammaglobulinemia." (PMID 38773012, 2024).
immunodeficiency (1 paper, 2024). Failure of the immune system to protect the body adequately from infection, due to the absence or insufficiency of some component process or substance. "Thus, despite the widespread expression of PRIM1 in immune cells, the isolated B cell lymphopenia was the only feature of a lymphocyte immunodeficiency that we could detect in P1." (PMID 38773012, 2024).
intervertebral disc degeneration (1 paper, 2025).
lipodystrophy (1 paper, 2020). A congenital or acquired disorder characterized by abnormal loss or redistribution of the adipose tissue in the body. "Likewise, reduced subcutaneous fat in PRIM1-deficient individuals parallels the lipodystrophy found in POLD1 cases (who had normal growth) due to heterozygous single-codon deletion of the catalytic site of Pol δ." (PMID 33060134, 2020).
Stroke (1 paper, 2023). Sudden impairment of blood flow to a part of the brain due to occlusion or rupture of an artery to the brain. "Multiple variants in the SLCO1B1, PRIM1, APOB, TYK2, TSEN15, CYP4F2, and MST1 genes were previously suggested as risk factors for stroke with p-values < 1.0 × 10−5 in a GWAS on German pediatrics." (PMID 37895268, 2023).
tumor (12 papers, 2019 to 2024). "Similar with ORA, PRIM1 was implicated in various tumor-related biological processes, including cell cycle, DNA replication, DNA repair, and autophagy." (PMID 33622397, 2021). "Carcinogenic pathways caused by PRIM1 may be influenced by factors in the tumor microenvironment, such as smoking (nicotine)." (PMID 35889263, 2022). "Orthotopic primary tumors and MRLs were generated, as above, from H2B-eGFP-labeled HER2/neu-Prim1 or Wnt1-Prim1 tumor cells, and osmotic pumps were employed to deliver bromodeoxyuridine (BrdU) for 2 weeks prior to sacrifice." (PMID 34088357, 2021). "Recently, emerging evidence has shown that PRIM1 acts as an oncogene that enhances the aggressive behaviors of tumor cells." (PMID 33622397, 2021). "H2B-eGFP-labeled HER2/neu-Prim1 or Wnt1-Prim1 tumor cells were used to generate orthotopic primary tumors, 28-day MRLs, and recurrent tumors." (PMID 34088357, 2021). "Whereas greater than 90% of HER2/neu-Prim1 and Wnt1-Prim1 primary tumor cells were labeled with BrdU over the 2-week period prior to sacrifice, fewer than 9% of HER2/neu-Prim1 and Wnt1-Prim1 residual tumor cells incorporated BrdU over the same time period." (PMID 34088357, 2021). "High expression of PRIM1 was correlated with tumor size, Edmondson-Steiner grade, ascites, and advanced TNM stage." (PMID 33622397, 2021). "GSEA showed that PRIM1 overexpression was significantly enriched in several tumor-related signaling pathways." (PMID 32908930, 2020). "BEL-7404 and SMMC-7721 carrying PRIM1 gene were used for oncogenesis in vitro to observe the weight and fluorescence intensity of the tumor." (PMID 33046981, 2020). "OS tumour xenografts showed a strong PRIM1 expression, which was less evident in GCTB and CS." (PMID 39409160, 2024). "The xenograft model was employed to detect the roles of PRIM1 in tumor growth in vivo." (PMID 33622397, 2021). "In addition, silencing UBE2C inhibited the proliferation, colony formation, tumor spheroid growth, and sorafenib resistance induced by exogenous PRIM1." (PMID 33622397, 2021). "Moreover, 3D spheroid model indicated that PRIM1 facilitated tumor growth and chemoresistance of sorafenib." (PMID 33622397, 2021). "Finally, the 3D spheroid model was conducted to validate the role of PRIM1 in tumor growth and sorafenib resistance." (PMID 33622397, 2021). "Additionally, the correlations between tumor-infiltrating immune cells (TIICs) and PRIM1 expression were evaluated." (PMID 32908930, 2020). "These evidences suggested that PRIM1 might contributed to tumor growth and sorafenib resistance." (PMID 33622397, 2021). "Besides, PRIM1 was also identified as a predictor that indicated poor survival of tumor patients." (PMID 33622397, 2021). "Suppression of the POLQ, PRIM1 and RPA1 genes increased the radiosensitivity of tumour cells, while overexpression conferred increased resistance.Therefore, these genes could be potential therapeutic targets to improve the efficacy of radiotherapy." (PMID 39132508, 2024). "Consistent with our observations in intact tumor-bearing MTB;TetO-HER2/neu;TTC; rYFP mice and in mice bearing orthotopic HER2/neu-Prim1 primary tumors, we did not observe enrichment for TICs among residual tumor cells when injected into mice on doxycycline." (PMID 34088357, 2021).
cancer (10 papers, 2016 to 2024). A tumor composed of atypical neoplastic, often pleomorphic cells that invade other tissues. "We transduced four patient-derived cancer cell lines that naturally exhibit either rs2277339 allele with AS sgRNA and verified that AS sgRNA disrupts PRIM1 in PRIM1S genetic contexts." (PMID 32433464, 2020). "Notwithstanding, it is well known that gene repair is one of the most relevant mechanisms of resistance to anti-cancer drugs and two proteins related to DNA repair, PRIM1 and POLB, were detected in both EV subpopulations (CTB and AV) in NR patients." (PMID 31014274, 2019). "DNA primase subunit 1 (PRIM1) has been reported as a novel oncogene in several cancer types." (PMID 33622397, 2021). "DNA Primase Subunit 1 (PRIM1) is crucial for cancer development and progression." (PMID 32908930, 2020). "While we have rigorously validated PRIM1 and EXOSC8 as genetic dependencies in cancer, further work is necessary to explore potential therapeutic modalities for targeting them (Supplementary Discussion)." (PMID 32433464, 2020).
infection (3 papers, 2020 to 2025). The state of being infected such as from the introduction of a foreign agent such as serum, vaccine, antigenic substance or organism. "In order to assay PRIM1 knockout efficiency before cells started to die due to loss of the essential PRIM1 protein, we performed deep sequencing on DNA collected from cells at the early time point of four days post-infection." (PMID 32433464, 2020). "Host proteins enriched at cellular replication forks during infection included DNA processing factors such as GINS, TOP2A, PRIM1/2, RPA2 and XRCC1; DDR signaling proteins such as CSNK2A1/3; cell cycle regulator proteins such as TFDP2 and SFN1; as expected for cells undergoing replication stress." (PMID 40825038, 2025).
PRIM1 also shares sentences with these, for which no sentence is quoted: colorectal cancer (2 papers); bladder cancer (1); chronic myeloid leukemia (1); COVID-19 (1); developmental delay (1); Fanconi anemia (1); glioblastoma (1); hematologic disorder (1); HIV-1 infection (1); IMAGe syndrome (1); lentivirus infection (1); lung (1); lung carcinoma (1); lymphopenia (1); mammary adenocarcinomas (1); primordial dwarfism (1); Seckel syndrome (1); Thrombocytopenia (1).